DOCK8 (dedicator of cytokinesis 8)
Diseases named in the same sentence as DOCK8 in open-access papers (continued):
Sharing a sentence is not in itself a finding about the gene and the disease.
hepatocellular carcinoma (3 papers, 2015 to 2023). A malignant tumor that arises from hepatocytes. "It has been shown that DOCK8 promotes the mesenchymal-type movement of hepatocellular carcinoma (HCC) cells, and the expression of DOCK8 is negatively correlated with the occurrence of HCC." (PMID 38139431, 2023). "DOCK8 was reported to expressed in different cancers, such as hepatocellular carcinoma and some epithelial cancers." (PMID 27980454, 2016).
IPEX syndrome (3 papers, 2016 to 2023). "Of these patients, three had SCID (1 Artemis, 2-RAG1), four had CVID, three had AIRE, one had DOCK8 deficiency, one had IPEX syndrome, one had CGD, one had STAT1, and one had PIK3CD." (PMID 36211419, 2022).
leukemia (3 papers, 2022 to 2024). A malignant (clonal) hematologic disorder, involving hematopoietic stem cells and characterized by the presence of primitive or atypical myeloid or lymphoid cells in the bone marrow and the blood. "DOCK8 mutation and deficiency were detected in the B-cell lymphocytic leukemia patient and acute myeloid leukemia (AML) patient, respectively which implies that DOCK8 deficiency or mutation may contribute to the occurrence of leukemia." (PMID 36386145, 2022).
melanoma (3 papers, 2018 to 2022). A malignant, usually aggressive tumor composed of atypical, neoplastic melanocytes. "A combination of meta-analysis of nevus GWAS and melanoma GWAS confirmed that the single-nucleotide Polymorphism (SNPs) of DOCK8 reached a global significant level, although DOCK8 has not been considered an important gene in the pathogenesis of melanoma." (PMID 36386145, 2022). "By contrast, HDAC4 and DOCK8 are in pathways that have not been implicated as important to nevogenesis or melanoma pathogenesis." (PMID 30429480, 2018). "In a bivariate analysis combining the nevus results with a recent melanoma GWAS meta-analysis (12,874 cases, 23,203 controls), SNPs near GPRC5A, CYP1B1, PPARGC1B, HDAC4, FAM208B, DOCK8, and SYNE2 reached global significance, and other loci, including MIR146A and OBFC1, reached a suggestive level." (PMID 30429480, 2018).
neuroblastoma (3 papers, 2016 to 2022). Neuroblastoma (NB) is the most common solid, extracranial childhood tumor. "Abnormalities on chromosome 9 of DOCK8 were also found in some high-risk neuroblastoma patients, in situ mouse models and 3D neuroblastoma models." (PMID 36386145, 2022). "An exon sequence result of 16 patients with primary and recurrent neuroblastoma showed that DOCK8 mutations were detected in two patients and deletion of chromosome 9p was detected in another five patients." (PMID 36386145, 2022). "Furthermore, a considerable number of neuroblastoma patients are accompanied with DOCK8 mutation or deletion." (PMID 36386145, 2022). "Duplication in DOCK8 was detected in one patient (BC40) and was found to be associated with neuroblastoma and hematologic neoplasms." (PMID 33503040, 2021). "DOCK8 mutations and YAP activation were reported to be associated with neuroblastoma relapse in one study." (PMID 27980454, 2016). "Additionally, we found that DOCK8 and the Hippo signaling pathway could play a role in neuroblastoma relapse." (PMID 27980454, 2016). "In addition, it was found that DOCK8 showed a higher expression in mouse stromal Schwann cells (SW10) and lower expression in neuroblastoma cell SK-N-BE 2)." (PMID 36386145, 2022).
progressive multifocal leukoencephalopathy (3 papers, 2018 to 2025). Progressive multifocal leukoencephalopathy (PML) is a neurological disorder that damages the myelin that covers and protects nerves in the white matter of the brain. "Rituximab also has a black box warning for progressive multifocal leukoencephalopathy (PML), and this risk should be considered prior to use in patients with other risks such as IEI with increased risk of PML (e.g., STAT1 gain-of-function [GOF], DOCK8 deficiency, and severe CD4 lymphopenia)." (PMID 41608118, 2025).
sclerosing cholangitis (3 papers, 2019 to 2022). A chronic, autoimmune inflammatory liver disorder characterized by narrowing and scarring of the lumen of the bile ducts. "Sclerosing cholangitis, a rare symptom, reported in only 5% of a large series including 136 DOCK8 deficient patients was observed in this patient." (PMID 36703986, 2022). "Hypomorphic function and somatic reversion of DOCK8 resulted in an incomplete phenotype and sclerosing cholangitis (SC) was incidentally diagnosed." (PMID 33936120, 2021).
X-linked lymphoproliferative disease (3 papers, 2015 to 2021). X-linked lymphoproliferative disease is a hereditary immunodeficiency characterized, in the majority of cases, by an inadequate immune response to infection with the Epstein-Barr virus (EBV). "Moreover, we will summarize the evidence pointing to a compromised conjugate formation in WIP, DOCK8, and X-linked lymphoproliferative syndrome." (PMID 26379669, 2015). "Reversion mutations have also been identified in other IEI, including in patients with leukocyte adhesion deficiency type-1 (LAD-1), X-linked lymphoproliferative disease (XLP), and DOCK8 deficiency." (PMID 33864184, 2021).
anaphylaxis (2 papers, 2018 to 2022). An acute hypersensitivity reaction that occurs from exposure to an allergen. "Studies in DOCK8-deficient mice have recently identified a novel CD4+ T-cell subset, Tfh13, which drives high-affinity IgE responses following allergen exposure and promotes anaphylaxis." (PMID 35572516, 2022).
autoimmune uveitis (2 papers, 2018 to 2023). An autoimmune form of uveitis (disease). "We propose that the decreased expression levels of these potential key players in autoimmune uveitis and the deviant signaling pathways driven by DOCK8 promote autoreactive inflammatory processes." (PMID 30120291, 2018). "Additionally, the decreased expression level of DOCK8 and the abnormal signaling pathway driven by DOCK8 in autoimmune uveitis can promote the process of auto‐reactive inflammation." (PMID 37647440, 2023).
Autosomal dominant hyper-IgE syndrome (2 papers, 2019 to 2023). 2000 IU/ml), recurring staphylococcal skin abscesses, and recurrent pneumonia with formation of pneumatoceles. "For others, IgE plasma levels are elevated: DOCK8 deficiency, autosomal dominant hyper-IgE syndrome (AD-HIES) Job’s syndrome, Comel-Netherton syndrome, PGM3 deficiency, IPEX (immune dysregulation, polyendocrinopathy, enteropathy X-linked) and Tyk2 deficiency." (PMID 31290545, 2019).
autosomal dominant mental retardation 2 (2 papers, 2021). "Heterozygous disorder of DOCK8 due to chromosomal deletion or a translocation breakpoint is related to autosomal dominant mental retardation 2 (OMIM 614113)." (PMID 34465353, 2021).
behavioral disorders (2 papers, 2021). "DOCK8 also plays an important role in brain development and cognitive function, which are associated with mental or behavioral disorders." (PMID 34465353, 2021).
colitis (2 papers, 2018 to 2021). Inflammation of the colon. "Subsequently, IPEX-like phenotype and active colitis have been associated with DOCK8 deficiency." (PMID 33936120, 2021). "Defective macrophage differentiation and IL-10-dependent STAT3 phosphorylation in DOCK8-deficient macrophages further strengthens our conclusion that WASP, together with DOCK8, regulates anti-inflammatory macrophage function and protects from colitis development." (PMID 29725003, 2018).
COVID-19 (2 papers, 2023 to 2025). A disease caused by infection with severe acute respiratory syndrome coronavirus 2. "For now, further exploration of the association and role of fHLH genes and DOCK8 in severe COVID-19 CSS is worthy of exploration." (PMID 40872807, 2025). "Mutations in novel and related sHLH-associated genes, DOCK2 and DOCK8, which are important for lymphocyte cytolytic activity, have also been linked to severe COVID-19 and post-COVID-19 multi-system inflammatory syndrome in children (MIS-C), respectively." (PMID 40872807, 2025). "Along these lines a DOCK8 mutation was reported among a cohort of 8 fatal cases of COVID-19 with CSS." (PMID 40872807, 2025). "FV transduction of NK-92 cells allowed for co-expression of WT or severe COVID-19 patient-derived DOCK8 missense mutation along with EGFP for cell sorting." (PMID 40872807, 2025). "It seems unlikely, however, that DOCK8 gene mutations are as frequent as in the severe COVID-19 cohort in this study." (PMID 40872807, 2025). "It is quite remarkable that 20% of the severe COVID-19 patients sequenced from this clinical trial possessed DOCK8 mutations, and 10% (4/39) of MIS-C children who underwent DNA sequencing had DOCK8 mutations." (PMID 40872807, 2025). "In exploring immune gene mutations by whole genome sequencing (WGS) among 20 of the severe COVID-19 patients enrolled in the anakinra clinical trial, several fHLH genes and DOCK8 mutations were identified in the cohort." (PMID 40872807, 2025). "Presumably, disruptive DOCK8 mutations contribute to CSS in severe COVID-19 as well." (PMID 40872807, 2025). "Rare heterozygous CSS gene (fHLH genes and DOCK8) mutations were frequently (45%) identified in this severe COVID-19 cohort, and DOCK8 missense mutations may contribute to CSS via diminished lymphocyte cytolytic activity." (PMID 40872807, 2025). "Thus, mutations in fHLH and DOCK8 genes may serve as risk alleles for developing severe COVID-19 with features of CSS upon infection with SARS-CoV-2." (PMID 40872807, 2025). "In this severe COVID-19 cohort, 45% (9/20) of those undergoing WGS possessed heterozygous mutations in fHLH and/or DOCK8 genes." (PMID 40872807, 2025). "Thus, DOCK8 may be a risk allele for COVID-19 CSS development." (PMID 40872807, 2025). "As the 3 missense DOCK8 mutations identified in this severe COVID-19 cohort had not previously been functionally tested, cDNA for the individual DOCK8 mutations were generated for use in FV transduction of the human NK cell line, NK-92 (see Section 2)." (PMID 40872807, 2025). "DOCK8 missense mutations have been shown to diminish lymphocyte cytolytic activity in CSS patients with infection triggered CSS, autoimmune triggered CSS, as well as the post-COVID-19 CSS, MIS-C." (PMID 40872807, 2025). "Being so sensitive, the ferritin–ESR ratio identified severe COVID-19 patients regardless of DOCK8 or fHLH mutation, likely reflecting other risk factors for severe disease in those without known CSS gene mutations." (PMID 40872807, 2025). "Nonetheless, the ferritin to ESR threshold of 11.3 identified all (9/9) severe COVID-19 patients with a DOCK8 and/or fHLH gene mutation but also all of those without one of these mutations." (PMID 40872807, 2025). "Recently, including in the setting of the hyper-inflammatory (sHLH-like) post-COVID-19 multi-system inflammatory syndrome in children (MIS-C), patient-derived DOCK8 missense mutations have been shown to act in a partially dominant-negative manner to disrupt NK cell function." (PMID 36836791, 2023). "Whether or not DOCK8 is a risk allele for COVID-19 infection cannot be ascertained from this current study and is a limitation, as non-severe COVID-19 patients did not undergo WGS." (PMID 40872807, 2025). "Nonetheless, the small sample size of 20 severe COVID-19 patients who underwent CSS is a study limitation, and future studies are needed to replicate the role of DOCK8 in severe COVID-19." (PMID 40872807, 2025).
COVID-19 (continued). "Since 45% of the clinical trial participants who underwent WGS possessed mutations in fHLH and/or DOCK8 genes that may have contributed to CSS via partially disrupted NK cell cytolysis, the association of these mutations was compared with the various CSS (general and COVID-19 specific) CSS criteria." (PMID 40872807, 2025).
DiGeorge syndrome (2 papers, 2019 to 2025). "Disturbed distributions of lymphocyte subsets or combinations of lymphocyte subsets can also be observed in other PID cases such as patients with WAS, ATM, DOCK8 deficiency, or DiGeorge syndrome." (PMID 30886612, 2019).
epilepsy (2 papers, 2021 to 2022). A brain disorder characterized by episodes of abnormally increased neuronal discharge resulting in transient episodes of sensory or motor neurological dysfunction, or psychic dysfunction. "Many of these genes are associated with epilepsy and ictogenesis, including DPP10, DOCK8, IAH1, LRRC4C, and SLC6A5." (PMID 36506088, 2022).
glioma (2 papers, 2022 to 2023). A benign or malignant brain and spinal cord tumor that arises from glial cells (astrocytes, oligodendrocytes, ependymal cells). "Moreover, DOCK8 was found to be a new candidate gene negatively associated with the progression of low-grade gliomas." (PMID 36386145, 2022).
head and neck squamous cell carcinoma (2 papers, 2022 to 2023). A squamous cell carcinoma that arises from any of the following anatomic sites: lip and oral cavity, nasal cavity, paranasal sinuses, pharynx, larynx, and salivary glands. "In addition, the high expression of DOCK8 indicates that patients with HPV-positive head and neck squamous cell carcinoma (HNSCC) have a good prognosis and an elevated level of microenvironmental immune infiltration." (PMID 36851274, 2023). "Importantly, in human papillomavirus (HPV) positive head and neck squamous cell carcinoma (HNSCC), the expression of DOCK8 was positively correlated with the level of immune cell infiltration." (PMID 36386145, 2022).
influenza (2 papers, 2018 to 2024). An acute viral infection of the respiratory tract, occurring in isolated cases, in epidemics, or in pandemics; it is caused by serologically different strains of viruses (influenzaviruses) designated A, B, and C, has a 3-day incubation period, and usually lasts for 3 to 10 days. "This includes herpes viruses (HSV, VZV, EBV), HPV and molluscum for DOCK8-deficiency, and HSV1, HSV2, SARS-CoV2, influenza and live attenuated viral vaccines for IFNAR1-deficiency." (PMID 39098944, 2024). "However, as in the skin, DC-specific DOCK8-deficient mice had impaired Tfh cell priming as well as impaired antigen-specific humoral responses to both OVA and influenza (as measured by antigen-specific IgG and weight loss in response to a lethal influenza infection)." (PMID 30319629, 2018).
itch (2 papers, 2017 to 2019). "However, since CD4+ T cells from Dock8−/− OTII Tg mice also induced itch in vivo on transfer into CAG-OVA mice, antigen availability may be a determinant of the disease induction." (PMID 28067314, 2017).
lung squamous cell carcinoma (2 papers, 2011 to 2016). "Additionally, the original data from TCGA verified that ADAMTS8, DMBT1 and DOCK8 were downregulated in both lung adenocarcinoma and squamous cell carcinoma, whereas RSPO3 expression was upregulated in lung adenocarcinoma and downregulated in lung squamous cell carcinoma." (PMID 27980454, 2016).
Omenn syndrome (2 papers, 2016 to 2023). An inflammatory condition characterized by erythroderma, desquamation, alopecia, chronic diarrhea, failure to thrive, lymphadenopathy, and hepatosplenomegaly, associated with severe combined immunodeficiency (SCID). "After considering SCID/Omenn syndrome, other significant or transplantable conditions could be considered such as WAS, IPEX, DOCK8 deficiency, EDA-ID and CD40L/CD40 deficiency and others." (PMID 27222657, 2016).
periodontitis (2 papers, 2025). An acute or chronic inflammatory process that affects the tissues that surround and support the teeth. "The microbial profile described in DOCK8-deficient individuals with periodontitis included several high-virulence periodontal pathogens, such as Porphyromonas gingivalis, Treponema denticola, and Tannerella forsythia." (PMID 40871317, 2025). "In pediatric subjects with periodontitis and DOCK8 deficiency, in addition to these microorganisms, other bacterial species, such as Capnocytophaga spp." (PMID 40871317, 2025). "Although found in periodontitis, due to several immunological derangements, DOCK8 deficiency may also contribute to broader periodontal pathologies, including gingivitis and necrotizing gingivitis." (PMID 40150657, 2025). "The atopic phenotype in DOCK8 deficiency, through increased IgE levels and eosinophilic inflammation, may compromise epithelial barriers and facilitate microbial translocation, favoring, in turn, periodontitis development and/or progression." (PMID 40150657, 2025). "Conversely, fungi were absent in the remaining two subjects with periodontitis (66.67%), diagnosed with DOCK8 deficiency and Papillon–Lefèvre syndrome, respectively." (PMID 40150657, 2025).
polyendocrinopathy (2 papers, 2022 to 2023). "Furthermore, no bone pathology was recorded among patients with cluster of differentiation 40 ligand (CD40L) deficiency, dedicator of cytokine 8 d (DOCK8) deficiency, immune dysregulation, polyendocrinopathy, enteropathy X-linked (IPEX), or activated PI3K delta syndrome (APDS)." (PMID 36930409, 2023).
Primary hemophagocytic lymphohistiocytosis (2 papers, 2022 to 2024). "Rare heterozygous missense variants in genes responsible for primary hemophagocytic lymphohistiocytosis (LYST, STXBP2, PRF1, UNC13D, AP3B1, and DOCK8) were found in patients with MIS-C." (PMID 38397896, 2024). "Thirty-nine children were diagnosed with MIS-C, and 25.4% of the 39 MIS-C patients harbored rare heterozygous missense mutations either in primary hemophagocytic lymphohistiocytosis (pHLH) genes (LYST, STXBP2, PRF1, UNC13D, AP3B1) or the HLH-associated gene DOCK8 (four variants)." (PMID 35336791, 2022).
renal cell carcinoma (2 papers, 2022 to 2023). "In addition, the expression of DOCK8 was significantly decreased in patients with renal cell carcinoma which showed a poor overall survival time than that with high expression of DOCK8." (PMID 36386145, 2022).
squamous cell carcinoma (2 papers, 2016 to 2025). A carcinoma arising from squamous epithelial cells. "The results showed that the HOXA11-AS expression was negatively correlated with DOCK8 in squamous cell carcinoma (r = −0.124, P = 0.048) and lung adenocarcinoma (r = −0.176, P = 0.005)." (PMID 27980454, 2016). "The original data from TCGA verified that ADAMTS8, DMBT1 and DOCK8 were down-regulated in adenocarcinoma and squamous cell carcinoma, whereas RSPO3 was overexpressed in adenocarcinoma and down-regulated in squamous cell carcinoma." (PMID 27980454, 2016). "Besides, we found that the HOXA11-AS expression was negatively correlated with DOCK8 both in squamous cell carcinoma and lung adenocarcinoma." (PMID 27980454, 2016). "We found that RSPO3, ADAMTS8, DMBT1, DOCK8, STMN2, SPINK6 and TUSC3 were the co-genes of HOXA11-AS in lung adenocarcinoma whereas RSPO3, ADAMTS8, DMBT1, DOCK8, STMN2, SPINK6, TUSC3 and C8orf22 were the co-genes of HOXA11-AS in squamous cell carcinoma." (PMID 27980454, 2016). "We found that RSPO3, ADAMTS8, DMBT1 and DOCK8 were all downregulated in squamous cell carcinoma tissues compared to non-cancerous lung tissues, whereas STMN2, TUSC3 and C8orf22 were upregulated in squamous cell carcinoma (all P < 0.001)." (PMID 27980454, 2016).
T-cell deficiency (2 papers, 2020 to 2022). "Patients with HIES accompanied by warts and T-cell deficiency can be strongly suspected to have DOCK8 deficiency." (PMID 33251169, 2020).
Alzheimer disease (1 paper, 2020). A progressive, neurodegenerative disease characterized by loss of function and death of nerve cells in several areas of the brain leading to loss of cognitive function such as memory and language. "Examples of known human genes associated with memory also identified in our study include: NTM and KLHl20 that are associated with Alzheimer’s disease and DOCK8 and KANK1 that are associated with neurodevelopmental disorders including memory potential." (PMID 32299497, 2020).